ONECUT2 (one cut homeobox 2)
Diseases named in the same sentence as ONECUT2 in open-access papers (continued):
Sharing a sentence is not in itself a finding about the gene and the disease.
bladder cancer (7 papers, 2018 to 2025). "For example, several studies have reported that ONECUT2 methylation combined with other biomarkers can effectively discriminate bladder cancer from benign disease." (PMID 37726806, 2023). "More recently, a combination of methylation status of TWIST, ONECUT2, and OTX1 with mutational analyses of FGFR3, TERT, and HRAS has been reported to detect bladder cancer with a sensitivity of 97% and a specificity of 83%." (PMID 29907142, 2018). "Consistently, ONECUT2 methylation alone in our study was present in 8 of 10 bladder cancer patients and 10 of 10 recurrent patients, indicating the potential role of ONECUT2 methylation in bladder cancer diagnosis." (PMID 37726806, 2023). "Techniques for detecting bladder cancer based on urine DNA or RNA, such as the detection of mutations and methylation of telomerase reverse transcriptase (TERT), Fibroblast growth factor receptor 3 (FGFR3), Vimentin (VIM), and One Cut Homeobox 2 (ONECUT2) genes, have become the focus of research." (PMID 41281744, 2025). "For example, one research detects the DNA methylation status of TWIST1, ONECUT2 (2 loci) and OTX1 in urine to diagnose bladder cancer among hematuria patients." (PMID 40855090, 2025). "By detecting methylation of specific bladder cancer-related methylation markers such as TERT promoter and ONECUT2 CpG sites, the method achieved a sensitivity of 94.0%, specificity of 93.1%, and an AUC of 0.961 in the validation dataset." (PMID 40191434, 2025). "A combination of five methylation markers (ONECUT2, MEIS1, OSR1, OTX1, and SIM2) resulted in a bladder cancer prediction model, with a sensitivity of 85% and a specificity of 87%." (PMID 37627900, 2023). "In urine samples, the methylation status of a urinary biomarker panel (HOXA9, ONECUT2, PCDH17, PENK, TWIST1, VIM, and ZNF154) showed great prediction accuracy in predicting bladder cancer in patients with hematuria." (PMID 37627900, 2023). "Here, we established a combination methylation assay of HOXA9, ONECUT2, PCDH17, PENK, TWIST1, VIM and ZNF154, which had displayed great prediction accuracy of bladder cancer in patients with hematuria by using urine samples." (PMID 31777606, 2019). "In conclusions, a urinary combined methylation assay of HOXA9, ONECUT2, PCDH17, PENK, TWIST1, VIM and ZNF154 displayed accurate prediction of bladder cancer in hematuria patients, which provided the guidance for the patients at early stage tumor and during the follow-up after operation." (PMID 31777606, 2019).
non-small cell lung carcinoma (5 papers, 2020 to 2025). A group of at least three distinct histological types of lung cancer, including non-small cell squamous cell carcinoma, adenocarcinoma, and large cell carcinoma. "THUMPD3-AS1 can regulate self-renewal by ceRNA network of miR-543 and ONECUT2 associated with non-small cell lung cancer." (PMID 34966747, 2021). "Among them, THUMPD3-AS1 may have an impact on Non-Small Cell Lung Cancer cell growth and self-renewal through controlling miR-543 and ONECUT2." (PMID 36568384, 2022).
prostate adenocarcinoma (4 papers, 2019 to 2026). "ONECUT2 expression in prostate adenocarcinoma synergizes with hypoxia to suppress androgen signaling and induce neuroendocrine plasticity." (PMID 41545903, 2026). "ONECUT2 is active in prostate adenocarcinoma as a lineage plasticity driver, but also promotes neuroendocrine prostate cancer (NEPC), a highly aggressive variant that emerges as a result of AR-targeted therapy and ONECUT2 is active during hypoxia signaling." (PMID 41545903, 2026). "Following the discovery of ONECUT2 and its role in the transition from prostate adenocarcinoma to NEPC, new drugs targeting this pathway are being developed and studied in clinical trials." (PMID 35582526, 2022). "ONECUT2 ectopic expression in prostate adenocarcinoma synergizes with hypoxia to suppress androgen signaling and induce neuroendocrine plasticity." (PMID 30655535, 2019). "Specifically, ONECUT2 activates SMAD3, which regulates hypoxia signaling through moderating HIF-1α transcriptional binding, causing higher degrees of hypoxia in NEPC compared to prostate adenocarcinomas." (PMID 32509575, 2020). "To characterize ONECUT2 transcript expression in PCa, we interrogated several public databases, including TCGA PRAD (prostate adenocarcinoma) and other published (GSE) datasets." (PMID 41545903, 2026). "ONECUT2 expression is also elevated in a NEPC patient-derived xenograft (PDX) model LTL331R, which was developed from a hormone-naive prostate adenocarcinoma PDX model LTL331 through castration." (PMID 30655535, 2019). "Having demonstrated the function of ONECUT2 in NEPC, we further explored its role in prostate adenocarcinoma." (PMID 30655535, 2019). "Specifically, ONECUT2 activates SMAD3, which regulates hypoxia signaling through modulating HIF1α chromatin-binding, leading NEPC to exhibit higher degrees of hypoxia compared to prostate adenocarcinomas." (PMID 30655535, 2019).
lung adenocarcinoma (3 papers, 2019 to 2023). A carcinoma that arises from the lung and is characterized by the presence of malignant glandular epithelial cells. "ONECUT2 expression was associated with poor prognosis of RAS-driven lung adenocarcinoma." (PMID 31882655, 2019). "Our findings demonstrate that ONECUT2 is a lineage-specific and context-dependent oncogene in lung adenocarcinoma and suggest that ONECUT2 is a potential therapeutic target for these tumors." (PMID 31882655, 2019). "In this study, we reveal a context-dependent oncogenic role and epigenetic basis for the transcriptional regulation of ONECUT2 in lung adenocarcinoma." (PMID 31882655, 2019). "Here, we report that ONECUT2 is a lineage-specific and context-dependent oncogene in lung adenocarcinoma." (PMID 31882655, 2019). "ONECUT2 expression is significantly higher in human tumor samples of SCLC compared with lung adenocarcinoma, and in poorly differentiated neuroblastoma compared with glioma, consistent with the observation in CCLE cell line data." (PMID 30655535, 2019). "While ASCL1 was also overexpressed in a subset of lung adenocarcinoma, the expression of ONECUT2 and ASCL1 were barely correlated." (PMID 31882655, 2019). "Moreover, tissue microarray of lung adenocarcinoma and matched adjacent normal specimen showed that ONECUT2 was stained in 21 out of 75 tumor samples (nuclear positivity of 28%)." (PMID 31882655, 2019). "ONECUT2 may be an important therapeutic target in lung adenocarcinoma." (PMID 31882655, 2019). "We hypothesized that ONECUT2 promoted RAS-driven lung adenocarcinoma malignancy." (PMID 31882655, 2019). "However, in lung adenocarcinoma, ASCL1 expression seldom overlaps with ONECUT2." (PMID 31882655, 2019).
prostate tumors (3 papers, 2019 to 2025). "To evaluate the relationship between ONECUT2 and prostate tumor hypoxia, we used the ONECUT2 up-regulated genes in PC3 cells under hypoxic condition as a signature of ONECUT2 activity." (PMID 30655535, 2019).
small cell lung carcinoma (3 papers, 2019 to 2025). Small cell lung cancer (SCLC) is a highly aggressive malignant neoplasm, accounting for 10-15% of lung cancer cases, characterized byrapid growth, and early metastasis. "ONECUT2 was highly expressed in small cell lung cancer (SCLC), large cell neuroendocrine lung cancer (LCNEC) and lung carcinoid tumor (Carcinoid), a subtype with low-grade malignancy." (PMID 31882655, 2019).
neuroblastoma (2 papers, 2019 to 2023). Neuroblastoma (NB) is the most common solid, extracranial childhood tumor. "Therefore, the function of ONECUT2 in other types of NETs merits further investigation, especially in SCLC and poorly differentiated neuroblastoma." (PMID 30655535, 2019).
adenoma (1 paper, 2019). A neoplasm arising from the epithelium. "Moreover, PTPN13, SOX2 and ZEB2 showed detectable expression only in two out of 10 adenoma cases, whereas ONECUT2 and TGFB2 were up-regulated." (PMID 31623346, 2019). "All investigated and expressed target genes, CDKN1B, PTPN13, RND3, SOX2 and ZEB2, were down-regulated in adenoma compared to normal mucosa of CRC N0, except ONECUT2 and TGFB2, which were up-regulated." (PMID 31623346, 2019). "In contrast to adenoma, investigated target genes CDKN1B, PTPN13, RND3, SOX2 and ZEB2 were up-regulated in CRC N0, except ONECUT2 and TGFB2, which were down-regulated." (PMID 31623346, 2019). "In adenomas, differential expression in comparison with CRC N0 was also observed for ZEB2 (p = 0.034) and SOX2 (p = 0.046), and in comparison with CRC N+, ONECUT2 (p = 0.006) and RND3 (p < 0.001)." (PMID 31623346, 2019).
anaplastic large cell lymphoma (1 paper, 2024). Anaplastic large cell lymphoma (ALCL) is a rare and aggressive peripheral T-cell non-Hodgkin lymphoma, belonging to the group of CD30-positive lymphoproliferative disorders, which affects lymph nodes and extranodal sites. "ONECUT2 was significantly expressed in cell lines derived from anaplastic large cell lymphoma (SR-786, SUP-M2), AML (NOMO-1, OCI-AML3), Hodgkin lymphoma (HDLM-2, KM-H2, L-1236, L-428) and multiple myeloma (LP-1, U-266)." (PMID 38474011, 2024). "Interestingly, LL-100 RNA-seq data of leukemia/lymphoma cell lines demonstrated elevated EPAS1 expression in ONECUT2-positive anaplastic large cell lymphoma (ALCL)-derived cell lines." (PMID 38474011, 2024).
brain tumor (1 paper, 2011). "Most importantly, comparison of each of the brain tumor type-specific networks revealed a network unique to PA that included repressed expression of ONECUT2, a gene frequently methylated in other tumor types, and 13 other uniquely predicted TF-gene interactions." (PMID 21745356, 2011).
colon cancer (1 paper, 2015). "For example, Onecut2 was proved to be one bona fide target of miR-429 in colon cancer." (PMID 25405387, 2015).
diabetes (1 paper, 2022). "During the early stages of diabetes, islet β cells are exposed to the inflammatory environment formed by pro-inflammatory cytokines; under these conditions, miR-29 overexpression inhibits the expression of the transcription factor, Onecut2, which is associated with defective insulin secretion." (PMID 36561684, 2022).
Failure to thrive (1 paper, 2025). Failure to thrive (FTT) refers to a child whose physical growth is substantially below the norm. "In ONECUT2 knockout mice, the lack of this gene led to failure to thrive during the critical period before weaning, with a 25–30% reduction in size and weight by postnatal day 19 and a higher mortality rate (only 70% survived before weaning)." (PMID 40646804, 2025).
gastric adenocarcinoma (1 paper, 2024). "Our review of the TCGA public database revealed a significant upregulation of ONECUT2 mRNA expression in most cancers, including gastric adenocarcinoma (STAD), compared to the corresponding non-tumor tissue." (PMID 38997271, 2024).
Hyperglycemia (1 paper, 2021). An increased concentration of glucose in the blood. "This miRNA is expressed in insulin-secreting cells where it can inhibit the releasing of insulin by suppressing the expression of onecut-2 (OC2) transcription factor and subsequently up-regulation of granuphilin in hyperglycemia conditions." (PMID 33995938, 2021).
leukemia (1 paper, 2024). A malignant (clonal) hematologic disorder, involving hematopoietic stem cells and characterized by the presence of primitive or atypical myeloid or lymphoid cells in the bone marrow and the blood. "To find CUX2 and ONECUT2 positive models for further analyses and experiments, we screened 100 leukemia/lymphoma cell lines using our benchmark RNA-seq dataset LL-100." (PMID 38474011, 2024).
lung carcinoid tumor (1 paper, 2019). A neuroendocrine neoplasm that arises from the lung. "Considering ASCL1 had been proved to be a lineage-specific oncogene in high-grade neuroendocrine lung cancer and high expression of ONECUT2 in lung carcinoid tumor, we believed that ONECUT2 was unlikely a driver oncogene in lung tumor with neuroendocrine differentiation." (PMID 31882655, 2019).
mucinous tumors (1 paper, 2021). "This process involves the increased expression of certain stomach‐restricted genes such as Hnf4α, Vsig1, Gkn3, Ctse and Onecut2 in Nanog‐deleted mucinous tumors." (PMID 33439550, 2021).
neuroendocrine prostate tumors (1 paper, 2019). "Particularly, ONECUT2 is overexpressed in poorly differentiated neuroendocrine prostate tumors, and its expression increases with tumor progression; in tumor cells, ONECUT2 acts as a regulator of hypoxia signaling and regulates HIF-1α binding to chromatin through SMAD3 activation." (PMID 31366128, 2019).
osteoarthritis (1 paper, 2025). A noninflammatory degenerative joint disease occurring chiefly in older persons, characterized by degeneration of the articular cartilage, hypertrophy of bone at the margins and changes in the synovial membrane. "LRA confirmed that the upstream target of miR‐144‐3p was TM1‐3P and the downstream target was ONECUT2, suggesting that the TM1‐3P/miR‐144‐3P/ONECUT2 axis improves knee inflammation and injury in osteoarthritis rats." (PMID 40067024, 2025).
peritoneal disease (1 paper, 2022). "In addition to the presence of peritoneal disease, by the transcriptome analysis of paired samples of neoplastic tissue and normal gastric mucosa, we have identified a group of six differentially expressed genes that predict poor prognosis: ONG, FABP1, LIF, ONECUT2, SFRP2, and GPA33." (PMID 35847866, 2022).
urothelial carcinoma (1 paper, 2025). A malignant neoplasm derived from the transitional epithelium of the urinary tract (urinary bladder, ureter, urethra, or renal pelvis). "In order to develop the methylation assay for detecting urothelial carcinoma, we conducted a screening of 14 CpG sites in 7 genes (HIST1H4F, SOX1-OT, Vim, Onecut2, Twist1, NRN1, POU4F2) based on the literature review." (PMID 40855090, 2025).
tumor (46 papers, 2008 to 2026). "Analysis of TCGA PRAD expression data revealed a significant increase in ONECUT2 expression in PCa, significantly associating with cancer presence, high Gleason score, high tumor stage, and positive lymph nodes (metastasis)." (PMID 41545903, 2026). "We also observed that increasing expression of ONECUT2 is associated with tumour growth and its spread through the bowel wall." (PMID 36140249, 2022). "Elevated ONECUT2 expression was positively correlated with increased tumor number, tumor encapsulation loss, microvascular invasion, poor tumor differentiation, and advanced TNM stage." (PMID 34839358, 2021). "Positive ONECUT2 expression was statistically related to an increased tumor number, tumor encapsulation loss, microvascular invasion, poor tumor differentiation, and advanced TNM stage." (PMID 34839358, 2021). "One cut homeobox 2 (ONECUT2) is a transcription factor related to tumor cell proliferation, which is closely associated with the EMT process of cancer cells." (PMID 33343628, 2020). "Positive ONECUT2 expression was significantly correlated with increased tumor number, tumor encapsulation loss, microvascular invasion, poor tumor differentiation, and advanced tumor-node-metastasis (TNM) stage and was predictive of a poor outcome in both HCC cohorts." (PMID 34839358, 2021). "Recent findings showcasing the efficacy of the ONECUT2 inhibitor CSRM617 in suppressing tumor growth and metastasis in mouse models have positioned ONECUT2 as a potential therapeutic target." (PMID 41545903, 2026). "ONECUT2 has been identified as a survival factor and a driver for tumor aggressiveness in CRPC and NEPC." (PMID 41545903, 2026). "The developmental transcription factor ONECUT2 (One cut domain family member 2; OC2) has been associated with tumor cell proliferation, epithelial-mesenchymal transition (EMT) and metastasis in several cancer types." (PMID 40500731, 2025). "Previous studies have suggested that ONECUT2 modulates tumor cell proliferation, migration, and differentiation by orchestrating key transcription factors and signaling pathways." (PMID 38997271, 2024). "Single-cell RNA-seq analysis revealed the enrichment of mTORC1 signaling gene clusters in tumor cells expressing ONECUT2, and AKT1 expression was observed in epithelial cells." (PMID 38997271, 2024). "Our results showed that ONECUT2 was overexpressed in 56.30% of GC tissue, with expression levels in tumor tissue exceeding those in adjacent non-tumor tissue." (PMID 38997271, 2024). "Our single-cell RNA sequencing analyses revealed enrichment of ONECUT2-positive tumor cells within clusters displaying TNFα signaling via NFκB." (PMID 38997271, 2024). "The role of ONECUT2, a multifunctional transcription factor, in tumor pathogenesis is currently under investigation." (PMID 38997271, 2024). "Following the growth curves of tumor volumes within the highest cell count groups (n = 5), we found that ONECUT2 overexpression correlated with a significant increase in tumor volume compared with the control group." (PMID 38997271, 2024). "Taken together, circDennd1b exerted a tumor promoting effect by sponging miR-145-5p and thus upregulated ONECUT2 in PA cells." (PMID 37444485, 2023). "ONECUT2 is a transcription factor related to tumor cell proliferation, angiogenesis, and metastasis." (PMID 37444485, 2023). "Tumor promoting effect of ONECUT2 on PA cells was characterized by a serious of in vivo and in vitro experiments and miR-145-5p can notably reverse these promoting effects mediated by ONECUT2 overexpression." (PMID 37444485, 2023). "It has been proved that ONECUT2 regulated the aggressive tumor biology in neuroendocrine prostate cancer through activating SMAD3-HIF1α signaling." (PMID 37444485, 2023). "Inhibition of ONECUT2 can be achieved using a small molecule named CSRM617 that reduces tumor size/weight and metastasis in xenograft models." (PMID 37761978, 2023).